KL (klotho)
Diseases named in the same sentence as KL in open-access papers (continued):
Sharing a sentence is not in itself a finding about the gene and the disease.
metabolic syndrome (31 papers, 2013 to 2025). A cluster of metabolic risk factors for CARDIOVASCULAR DISEASES and TYPE 2 DIABETES MELLITUS. "To further investigate the association between serum klotho levels and the occurrence of metabolic syndrome, we constructed a logistic regression model adjusting for above confounding factors." (PMID 38501099, 2024). "Logistic regression analysis was used to assess the association between serum klotho protein levels and metabolic syndrome, while Cox regression analysis was employed to examine the correlation between serum klotho levels and all-cause mortality." (PMID 38501099, 2024). "To investigate the relationship between serum klotho levels and the risk of mortality in patients with metabolic syndrome, we employed a multivariate Cox proportional hazards model, adjusting for above confounding factors." (PMID 38501099, 2024). "The results highlight the potential role of Klotho as a novel biomarker for early risk stratification and prognostication, as well as a promising therapeutic target for metabolic syndrome prevention and treatment." (PMID 38501099, 2024). "In the Cox regression model, elevated klotho levels were found to significantly reduce the risk of all-cause mortality among individuals with metabolic syndrome (HR [95% CI] Highest vs. lowest quartile: 0.68 [0.51-0.90], P=0.006)." (PMID 38501099, 2024). "The relationship between Klotho levels in patients with metabolic syndrome and all-cause mortality rate was assessed after excluding patients who died within 30 months of follow-up." (PMID 38501099, 2024). "In summary, our study reveals a robust inverse association between circulating Klotho levels and metabolic syndrome prevalence and mortality." (PMID 38501099, 2024). "In the present study, we aim to systematically assess the associations of serum Klotho levels with the prevalence and mortality of metabolic syndrome using a large nationally representative cohort." (PMID 38501099, 2024). "First, the cross-sectional design of the study limited causal inference between Klotho and metabolic syndrome." (PMID 38501099, 2024). "Several studies are currently investigating the potential association between the Klotho protein and dyslipidemia." (PMID 37352065, 2023). "This is the first study to demonstrate the association between metabolic syndrome and soluble Klotho protein concentration in generally healthy adults." (PMID 35053218, 2022). "In the adjusted model, Klotho protein concentration was inversely associated with the presence of metabolic syndrome (p = 0.013)." (PMID 35053218, 2022). "Furthermore, higher klotho levels strongly indicated a lower risk of all-cause mortality in individuals with metabolic syndrome." (PMID 38501099, 2024). "Our findings may provide novel insights into the pathogenic role of Klotho in metabolic syndrome and support Klotho as an independent prognostic biomarker." (PMID 38501099, 2024). "Moreover, higher Klotho levels strongly predicted lower risks of all-cause mortality among individuals with metabolic syndrome." (PMID 38501099, 2024). "However, after adjusting for age, gender, blood pressure, smoking, DM2, dyslipidemia, albuminuria and other cardiovascular risk factors and inflammatory markers, only the inverse association of serum Klotho with CIMT remained as statistically significant." (PMID 37274332, 2023). "Since FGF23 may be an indicator of the risk of metabolic syndrome, Klotho protein implies its role against metabolic diseases." (PMID 35053218, 2022). "Thus, the results of a forward stepwise multiple regression analysis performed with the SSI as the dependent variable showed the independent and positive association between the severity of stenosis with soluble Klotho, dyslipidemia and ACR (adjusted R2 = 0.153, p < 0.01)." (PMID 37686263, 2023).
metabolic syndrome (continued). "Thus, we speculated that the up-regulation of Klotho expression and functional link with other gene could also explain the observed association between the G-395A and the metabolic syndrome." (PMID 26880028, 2016). "It has been shown that soluble Klotho protein concentration is negatively correlated with the occurrence of metabolic syndrome, as well as abdominal obesity and hypertriglyceridemia." (PMID 40007807, 2025). "Furthermore, serum Klotho levels were inversely and independently associated with metabolic syndrome prevalence, suggesting that higher Klotho levels could lower the risk of all-cause mortality in metabolic syndrome." (PMID 40799848, 2024). "Our analysis reveals a significant L-shaped relationship between serum Klotho levels and CKD risk in individuals with metabolic syndrome." (PMID 39777219, 2024). "Several studies have suggested a potential relationship between dyslipidemia and cognitive dysfunction, although not in CKD, and notably, the NHANES study reported an inverse relationship between Klotho and dyslipidemia." (PMID 38673780, 2024). "Our findings add to the emerging evidence supporting Klotho as a key regulator of metabolic homeostasis and a potential therapeutic target for metabolic syndrome." (PMID 38501099, 2024). "Clarifying how Klotho protein interacts with the genome, microbiota, and other factors influencing metabolic syndrome will have substantial research implications." (PMID 38501099, 2024). "Our study provides compelling evidence supporting Klotho as a novel protective factor against metabolic syndrome and an independent prognostic predictor." (PMID 38501099, 2024). "The pleiotropic metabolic benefits make Klotho an attractive candidate biomarker and therapeutic target for metabolic syndrome." (PMID 38501099, 2024). "In light of the potential role of Klotho in metabolism-related diseases, recent studies begin to investigate the relationship between Klotho and metabolic syndrome, but the results remain inconsistent, especially regarding the prognostic value of Klotho." (PMID 38501099, 2024). "Current evidence regarding the effects of serum Klotho among patients with metabolic syndrome (MetS) is scarce." (PMID 39777219, 2024). "Further in vivo data are needed to support the physiological contributions of soluble Klotho protein independent to FGF23 in the mechanism of metabolic syndrome." (PMID 35053218, 2022). "Soluble Klotho protein is correlated with changing metabolic syndrome components in adults, especially central obesity and high TG levels." (PMID 35053218, 2022). "We aimed to figure out the correlation between Klotho protein and metabolic syndrome in generally healthy adults." (PMID 35053218, 2022). "Multivariate linear regression models were used to analyze the effect of soluble Klotho protein on the prevalence of metabolic syndrome." (PMID 35053218, 2022). "Our study showed the inverse correlation between Klotho protein and the presence of some components of the metabolic syndrome (abdominal obesity and high TG in a generally healthy adult population." (PMID 35053218, 2022). "A recent extensive cohort of U.S. adults, demonstrated an inverse relationship between serum Klotho levels and the incidence of metabolic syndrome and proposed recombinant Klotho protein administration as a promising new treatment strategy with already favorable outcomes in mouse models." (PMID 39857056, 2025). "Klotho likely ameliorates metabolic syndrome through diverse mechanisms." (PMID 38501099, 2024). "Klotho prevents ectopic soft tissue calcification to ameliorate metabolic syndrome complications." (PMID 38501099, 2024). "This study aims to explore the potential association between plasma klotho levels and various prognostic outcomes in CKD and ESKD, including all-cause mortality, cardiovascular events, metabolic syndrome development and adverse renal events necessitating renal replacement therapies." (PMID 39281418, 2024).
metabolic syndrome (continued). "Developing targeted Klotho-based therapies may provide innovative management strategies to stem the rising tide of metabolic syndrome worldwide." (PMID 38501099, 2024). "This review will discuss FGF21-mediated FGFR1/β-KL signaling pathways in the liver, adipose, and cardiovascular systems, as well as how this signaling is involved in the interplay of these organs during the metabolic syndrome." (PMID 35983184, 2022). "There was a positive association between serum klotho levels and no history of dyslipidemia (beta coefficient: 15.474, p = 0.0053)." (PMID 36221064, 2022). "Our study aimed to figure the correlation between Klotho concentration and metabolic syndrome." (PMID 35053218, 2022). "Soluble Klotho protein concentration was inversely correlated with the presence of metabolic syndromes (p = 0.013) and numbers of components that met the definition of metabolic syndrome (p < 0.05)." (PMID 35053218, 2022). "According to our result, there is a significant negative association between the prevalence of metabolic syndrome and Klotho protein concentration." (PMID 35053218, 2022). "The potential involvement of SNP G-395A in KLOTHO gene function and pathogenesis of the metabolic syndrome and these components remains speculative." (PMID 26880028, 2016). "As a crucial component of the FGF23 signaling pathway, Klotho could play a pivotal role in the pathogenesis of age-associated disorders via the FGF-23–Klotho axis, including cardiovascular disease, renal dysfunction, and metabolic syndromes." (PMID 40737282, 2025). "In this large nationally representative cohort of U.S. adults, we found a graded inverse association between serum Klotho levels and the prevalence of metabolic syndrome, independent of potential confounders including demographics, socioeconomics, and lifestyle factors." (PMID 38501099, 2024). "Therefore, Klotho effectively ameliorates metabolic syndrome by increasing serum calcium." (PMID 38501099, 2024). "Additionally, the RCS analysis confirmed a significant non-linear relationship between serum klotho levels and all-cause mortality risk in patients with metabolic syndrome (P value for non-linearity <0.0001, total P value <0.0001)." (PMID 38501099, 2024). "First, this is a cross-sectional study, it could not access causality between Klotho and metabolic syndrome." (PMID 35053218, 2022). "Vitamin D supplementation has been found to increase Klotho expression, while disturbances in this hormonal axis are common in individuals with increased WWI and metabolic syndrome." (PMID 40678338, 2025). "The correlation between Klotho and SSI was also observed even after additional adjustment for potential confounders: age, sex, HT, current smokers, dyslipidemia, ACR, body mass index (BMI), phosphorus, iFGF23, TNFα, IL6, and hs-CRP." (PMID 37686263, 2023). "The result of this study strengthens the potential of protective roles of Klotho protein and the possibility of independence to FGF families in metabolic syndrome and further therapeutic strategy." (PMID 35053218, 2022). "Our results pointed to Klotho as an independent determinant of ABI and CIMT, even after adjusting for age, gender, blood pressure, smoking, DM, dyslipidemia, and other factors." (PMID 34354161, 2021). "Given the strong association between sedentary behavior and chronic conditions like metabolic syndrome and inflammation, individuals with extended sedentary periods might experience greater suppression of Klotho expression, making the negative effects of caffeine more pronounced in this group." (PMID 39723163, 2024).
heart failure (30 papers, 2013 to 2025). Inability of the heart to pump blood at an adequate rate to meet tissue metabolic requirements. "The activation of DNA damage response, as observed in Klotho deficiency, has been linked to more severe pressure overload-induced heart failure." (PMID 40799848, 2024). "Klotho deficiency has been strongly implicated in heart failure and its associated pathological processes." (PMID 40799848, 2024). "Previous studies have shown that 17β ‐estradiol prevents Klotho deficiency from inducing heart failure by eliminating upregulation of Na‐Pi cotransporter expression in the kidneys of female mice." (PMID 35841322, 2023). "The results of one study showed that low Klotho concentration is associated with an increased risk of cardiovascular death or heart failure hospitalization in patients with stable ischaemic heart disease." (PMID 35509269, 2022). "Klotho deficiency leads to heart failure in Klotho-hypomorphic mutant (KL(−/−)) mice." (PMID 38203812, 2024). "In addition, there are several longitudinal studies assessing the association of Klotho with prognosis (cardiovascular death and rehospitalization for heart failure) in patients with cardiovascular disease." (PMID 35509269, 2022). "If stable and effective up-regulation can be achieved clinically through gene therapy, recombinant protein or Klotho-derived peptides in the future, it is expected to provide a new treatment strategy for the prevention of heart failure in diabetic patients." (PMID 41438297, 2025). "In progressive chronic kidney disease, increased levels of circulating FGF23 and low KL expression in the kidney lead to severe cardiovascular manifestations, including heart failure and ultimately death." (PMID 40006994, 2025). "Overall, the interplay between mitochondrial dysfunction, oxidative stress, and DNA damage, and the protective role of Klotho has significant implications for heart failure and other age-related cardiac conditions." (PMID 40799848, 2024). "The elevation of FGF23 and the deficiency of Klotho collaboratively contribute to the activation of the RAS and its well-known adverse downstream effects, including cardiac remodeling and heart failure." (PMID 38846254, 2024). "We established an IS-induced mouse model of heart failure and kidney damage to investigate the role of Klotho in vivo." (PMID 32464602, 2020). "In contrast, FGF-23 was significantly associated with mortality and heart failure hospitalization independent of Klotho levels." (PMID 40362897, 2025). "In the high-risk group (low Klotho and high FGF23), the number needed to treat (NNT) with trandolapril to prevent one cardiovascular death or heart failure hospitalization event was nine, representing a 25% reduction compared to risk stratification based on FGF23 alone (NNT=12)." (PMID 38846254, 2024). "Additionally, cardiac-specific overexpression of GR prevented excessive oxidative stress, apoptosis, and heart failure in KL (−/−) mice." (PMID 40799848, 2024). "Additionally, lower Klotho levels are associated with long-term cardiovascular (CV) events, such as CV death and heart failure rehospitalization, suggesting a potential protective effect of Klotho on the heart." (PMID 39330350, 2024). "Similarly, there is a possibility that Klotho is produced as a compensatory response and protects the heart during heart failure by acting as a suppressor of inflammation." (PMID 35509269, 2022). "One of the reasons for Klotho downregulation in type 2 CRS maybe the increase of circulatory tumor necrosis factor-α induced by heart failure." (PMID 33460402, 2021). "We investigated whether Klotho could alleviate IS-induced heart failure and kidney damage by regulating macrophages, which play a key role in the inflammatory response in CKD and AKI." (PMID 32464602, 2020). "This hypothesis can be supported by the evidence of increased serum Klotho level in patients after heart failure." (PMID 32319182, 2020).
heart failure (continued). "From this we hypothesize that local overexpression of sKlotho may compensate for Klotho-independent maladaptive effects of FGF23 in an autocrine or paracrine manner in human heart failure." (PMID 29849175, 2018). "Additionally, we evaluated whether baseline values of klotho and FGF-23 were associated with 1-month changes in peak oxygen consumption (peak VO2) in stable outpatients with heart failure with reduced ejection fraction (HFrEF)." (PMID 37745119, 2023). "In addition to uncovering a new action of klotho, these results could be clinically relevant for the treatment of heart failure." (PMID 24340070, 2013). "This substudy aimed to assess the changes in klotho and FGF-23 levels 1-month after dapagliflozin in patients with stable heart failure and reduced ejection fraction (HFrEF)." (PMID 37745119, 2023). "Not surprisingly, reduced Klotho levels and elevated FGF23 concentrations have been associated with increased hospitalizations for heart failure and the incidence of cardiovascular death in a population of 3555 patients with stable ischemic heart disease." (PMID 37061530, 2023). "Few studies have investigated the correlation between Klotho and specific cardiovascular disease (CVD), and the potential links between Klotho, renal function, and heart failure remain unknown." (PMID 35509269, 2022). "To date, no studies have reported the relationship between Klotho and the prognosis of patients with heart failure." (PMID 35509269, 2022). "Since we found no clear relation of sKlotho in the serum to heart failure outcomes we aimed to investigate Klotho expression directly in the human heart." (PMID 29849175, 2018). "Whereas klotho did not predict CV events (death, atherosclerotic events, and decompensated heart failure) in patients CKD stages 2–4, FGF23, on the other hand, was significantly associated with future decompensated heart failure." (PMID 32106499, 2020).